CD38 (CD38 molecule)
Diseases named in the same sentence as CD38 in open-access papers (continued):
Sharing a sentence is not in itself a finding about the gene and the disease.
tumor (continued). "Nonetheless, the addition of 225Ac CD38-TAT 14 days later increased the delay in tumor growth to 20 days compared to the untreated controls, or 10 days for CS1 CAR T monotherapy." (PMID 37209218, 2023). "The authors postulated a significant prognostically favorable impact of CD38-positive, tumor-infiltrating plasma cells for relapse-free survival." (PMID 37894900, 2023). "CD4+ T cells isolated from tumor tissue downregulate granzymes B and H and upregulate genes associated with regulatory T cells (FOXP3, IKZF4, CD38, ISG15)." (PMID 37648263, 2023). "In support of our data, the co-expression of CD38 with T cells exhaustion markers was also observed on dysfunctional or exhausted CD8+ T cells in other tumor models." (PMID 37377962, 2023). "On the contrary, NK cells expressing CD38 CAR under the control of CD38 endogenous promoters showed better tumor control." (PMID 37485647, 2023). "As result, several strategies have been found to increase tumor surface CD38, with the goal of boosting MoAb efficacy in co-treatment regimens." (PMID 36830052, 2023). "Increased adenosine production due to upregulation of CD38 by tumor cells was identified as another mechanism of resistance to PD-1 and PD-L1 checkpoint blockade, and inhibition of CD38 was shown to significantly improve responses to an anti-PD-L1 antibody." (PMID 37240219, 2023). "The Treg cells in the SCC16-0016 tumor dissociate expressed markers indicative of functional activation, with >80% of Treg cells expressing the activation markers CD38, ICOS, and OX40." (PMID 36934113, 2023). "When encapsulating cyclin D1 siRNA, anti-CD38-LNPs efficiently induced gene silencing and suppressed tumor cell proliferation in vivo, prolonging the survival of MCL-bearing mice." (PMID 38516300, 2023). "THE L82-pulsed DC vaccination in combination with anti-CD38 antibody treatment effectively inhibited the tumor growth by reducing the tumor- infiltrated regulatory T cells." (PMID 36761724, 2023). "We identified CD8+ TRM cells as the predominant CD38-expressing immune cells in TILs, and their association with the T cell exhaustion signature in HCC TME and the higher histopathological tumor grades." (PMID 37377962, 2023). "This combined treatment notably elevated CD4+ T-cell presence within the tumor microenvironment and increased IL-5 and IL-13 tumor levels, while simultaneously decreasing CD38 in the tumor stroma." (PMID 37689790, 2023). "Consistent with the data from the s.c. models, the number of CD38+CD39+CD4+ TILs in tumor foci in the lungs of mice injected with B7-H3 knockdown was increased compared to mice injected with control cells." (PMID 36869048, 2023). "Daratumumab (DARA) is an IgG1κ human monoclonal antibody (MAb) that binds to the CD38 protein, a surface protein that is expressed on MM cells, and inhibits the in vivo growth of CD38-expressing tumor cells." (PMID 37999125, 2023). "Daratumumab was shown to be a potent inhibitor of the in vivo and in vitro growth of CD38-expressing tumor cells to lead to the immune-mediated death of the tumor cells through multiple effector functions." (PMID 36834545, 2023). "It was also observed that some patients are naturally resistant to Daratumumab due to a low basal CD38 expression on tumor cells." (PMID 37532787, 2023). "Daratumumab, a monoclonal antibody against CD38, has shown promising anti-tumor activity in the treatment of MM." (PMID 37799465, 2023). "For U266 cells, CD38‐CAR‐T cells killed about 30% (average 30.87%) tumor cells, which was only 8.87% in control T cells." (PMID 37039305, 2023). "B7-H3 inhibition in mTORC1-hyperactive cells suppresses tumor growth by increasing IFN-γ responses and major histocompatibility complex II (MHC-II) expression in the tumor cells and enhancing CD38+CD39+CD4+ T lymphocyte-mediated antitumor immunity." (PMID 36869048, 2023).
tumor (continued). "Similar to the results in MM cell lines, CAR‐T cells also showed a significant cytotoxicity against CD38+ primary tumor cells isolated from MM patients." (PMID 37039305, 2023). "For example, a study identified a subpopulation of circulating CD8+ T cells, similarly enriched for expression of CD38 and HLA-DR, whose abundance within the primary tumor and within PBMCs changed after a 3-week course of checkpoint blockade therapy." (PMID 37735591, 2023). "Despite using an attenuated version of interferon, anti-CD38-(att)IFN-α sustained significant anti-tumor activity in various cell lines and was capable of completely eradicating the established NCI-H929 subcutaneous tumors in all tested mice." (PMID 36839658, 2023). "As CD38 is also expressed in NK cells, activated T cells, and muscle cells, there is a chance of developing “on-target, off-tumor” toxicity." (PMID 38006053, 2023). "Since our previous study has shown that the HCC TME is enriched with CD8+ tissue-resident memory cells (TRM) that play an important role in tumor immunity, we evaluated CD38 expression on CD8+ TRM (CD103+CD45RO+CD8+) in TILs and NILs." (PMID 37377962, 2023). "From CyTOF analysis, we compared the immune composition of CD38-expressing leukocytes in TILs, non-tumor tissue-infiltrating leukocytes (NIL), and peripheral blood mononuclear cells (PBMC)." (PMID 37377962, 2023). "Tumor growth delay was best for mice receiving CS1 CAR T cells 21 days post 225Ac-CD38 TAT (28 days post tumor engraftment) with an overall survival of 91 days compared to 42 days for untreated controls." (PMID 37209218, 2023). "The combination of anti-PD-1 (cemiplimab) and anti-CD38 (isatuximab) monoclonal antibodies resulted in the activation of peripheral T cells in patients with mCRPC and a median reduction in CD38+ tumor-infiltrating immune cells, from 40% to 3% (NCT03367819)." (PMID 37366915, 2023). "Pre-treating tumor cells with MHC-II blocking antibody inhibited CD38+CD39+CD25-CD4+ TIL-mediated tumor cell death." (PMID 36869048, 2023). "Here, we have investigated the metabolic events induced by CD38 upregulation in MM cells by focusing on their effects on the anti-tumor activity of NAD+-lowering agents." (PMID 36830052, 2023). "Tumor-infiltrating plasma cells were analyzed via immunohistochemistry using the plasma cell markers CD38 and IgκC." (PMID 37894900, 2023). "While other studies have demonstrated the potential roles of CD38+ tumor-associated macrophages in the clinical outcome of HCC patients, the role of CD38 in tumor-infiltrating T cells in the HCC TME remains to be further elucidated." (PMID 37377962, 2023). "Tumor plasma cells were identified using a combination of markers including CD38, CD138, CD45, CD2, CD14, CD19 and CD56." (PMID 37046814, 2023). "In patient #1, loss of cluster 2 and a gain of cluster 4 at resistance was detected, which is in line with a loss in the anti-tumor markers CD169, STING, and CD38." (PMID 37620318, 2023). "CD38 is prevalently expressed on normal and tumor plasma cells and anti-CD38 MoAbs have shown a significant efficacy to target MM cells." (PMID 37532787, 2023). "In this study, we demonstrated the use of readily translatable mIHC/IF methods to determine the pre-treatment expression of the 4-gene inflammatory signature and CD38 expression in the HCC tumor microenvironment." (PMID 37342338, 2023). "Concurrent inhibition of CD38 and PD‐L1 in these murine models has been shown to substantially reduce primary tumor burden and metastases." (PMID 36251503, 2023). "This interpretation is consistent with higher gene expression of effector- and division-associated genes (GZMB, IFNG, MKI67) in the untreated tumor and low expression of activation markers such as HLA-DR and CD38 in the irradiated tumor." (PMID 37209684, 2023). "The effective clearance of tumor cells by CD38‐CAR‐T cells requires a longer time or higher E:T ratios." (PMID 37039305, 2023).
tumor (continued). "PEL is a tumor of plasmablast-like B cells generally expressing CD38, the target of daratumumab (Dara)." (PMID 36632565, 2023). "In our previous studies, we identified a high percentage of CD19+CD24+CD38+ Bregs in the tumor microenvironment (TME) and peripheral blood of IBCa patients." (PMID 35935985, 2022). "ADCC is widely observed in CD38 mAb treatment and is the main mechanism of Isatuximab-induced tumor cell death in several lines of experiments." (PMID 35342342, 2022). "Studies have reported that the ratio of PD-1+CD38+T cells is related to poor prognosis, and CD38-mediated immunosuppression is one of the mechanisms for tumor cells to escape PD-1/PD-L1 block." (PMID 35725444, 2022). "Tumor-infiltrating CD38+ CD8+ T cells were significantly less capable of secreting IFN-γ and granzyme B than their adjacent normal tissues, and negative costimulatory markers PD-1 and CD101 were also increased in this subpopulation." (PMID 35906622, 2022). "The proportion of tissue-resident CD8+ T cells with high PD-1 expression in tumor tissues was significantly higher than in paratumor tissues, and this cell population also highly expressed CD38." (PMID 35725444, 2022). "The aim of our study was to generate a fluorochrome-conjugated nanobody recognizing an epitope of CD38 distinct from that of daratumumab to detect tumor cells under daratumumab therapy in vitro, ex vivo, and in vivo." (PMID 36389758, 2022). "ATRA elevated CD38 expression in multiple CD38low cancer cells and enhanced the anti-tumor activity of daratumumab and CD38-CAR T cells in xenograft tumors." (PMID 35765110, 2022). "Calculation of tumor-to-background ratios (T/B-ratio) confirmed a rapidly increasing T/B-ratio of CD38-positive tumors after injection of JK36AF680 in both saline-pretreated and daratumumab-pretreated mice." (PMID 36389758, 2022). "Gene expression profiling of CD38+ and CD38− members of the same clone highlighted elevated levels of VEGF and Mcl-1 in CD38+ cells, conferring a survival advantage potentially from CD38-mediated interactions with the tumor microenvironment." (PMID 36139103, 2022). "Similar to other mechanisms that are hijacked and serve to pro-tumor purposes, tumor cells can benefit from the expression of ectonucleotidases, mainly CD38, CD39, and CD73." (PMID 36581667, 2022). "In the hypoxic TME, the increased enzymatic functions of CD38 result in an tumor-friendly environment, leading to increased immune cell resistance in tumors as well as faster growth and proliferation rates." (PMID 36233088, 2022). "When the tumor size approached ~ 100 mm3 (18–20 days), two doses of 8 × 106 CD38-CAR T cells were delivered intravenously." (PMID 35765110, 2022). "Lastly, high levels of expression of certain tumor-associated antigens (TAAs; CD19, CD20, CD22, and CD38) in most B cell malignancies are correlated with a high proliferation rate and disease progression." (PMID 36551511, 2022). "Specifically, combining an anti-PD-L1 antibody and an anti-CD38 antibody suppressed primary tumor growth and metastases more than either treatment alone." (PMID 36078044, 2022). "CD38+ tumor-infiltrating immune cells ((TIICs), including B-cells and myeloid cells) density increase the following progression to castration-resistant prostate cancer (CRPC) and shortens OS." (PMID 36077708, 2022). "ATRA induced CD38 expression within the xenograft tumors, and both combinations exhibited more robust anti-tumor activities than the monotherapies." (PMID 35765110, 2022). "The inhibition of CD38 expression on tumor cells reduces adenosine production and improves the efficacy of immune checkpoint therapy, demonstrating greater accumulation of CD8+ T cells and lower levels of Treg cells in mouse tumor models." (PMID 36569893, 2022). "These activated CD38+ tumor infiltrating lymphocytes (TILs) produce cytotoxic compounds and inflammatory cytokines to attack tumors." (PMID 35251964, 2022).
tumor (continued). "M2 (F4/80+CD38-Egr2+) macrophages, like MDSCs, are immunosuppressive, while M1 (F4/80+CD38+Egr2-) macrophages mediate anti-tumor immune responses." (PMID 35697801, 2022). "CD38 is silenced in tumor cells likely because metabolically active cells rely upon NAD+ and NAD+-dependent enzymes for glycolysis and mitochondrial biogenesis." (PMID 36077708, 2022). "Among the different mechanisms regulating the resistance to the checkpoint inhibitors, the up-regulation of CD38 by tumor cells causes a functional impairment of CD8 T cells, favoring the tumor immune escape." (PMID 35563517, 2022). "Next, to evaluate the potential of #5-CD38-IgG1 to recruit different components of the immune system for tumor cell lysis, standard chromium release assays with PBMC or serum of healthy donors and CD38-positive tumor cell lines were performed." (PMID 35784366, 2022). "Akin to other mAbs, CD38 antibodies inhibit tumor cell growth through complement-dependent cytotoxicity (CDC), antibody-dependent cytotoxicity (ADCC), and antibody-dependent macrophage phagocytosis (ADCP) and induce apoptosis." (PMID 36313735, 2022). "The current research on CD38 and tumors confirms that CD38 has important functions in promoting tumor cell growth and immune escape." (PMID 35758066, 2022). "For example, in 27–46% of patients with chronic lymphocytic leukemia (CLL), CD38 expression was found on tumor B cells." (PMID 36611312, 2022). "Daratumumab in combination with the Fc-silent CD47 blocking antibody hu5F9-IgG2σ achieved statistically significantly increases in phagocytosis of T-ALL cell lines and primary tumor cells compared to CD38 antibodies alone." (PMID 36052078, 2022). "CD38 is not only expressed by tumor cells, but also by regulatory B and T cells as well as by myeloid suppressor cells and NK cells." (PMID 36405759, 2022). "When treatments were administered before tumors were established (on day 10 post tumor cell inoculation), 4 of 5 mice were tumor-free upon CD38-CAR T-cell treatment." (PMID 35765110, 2022). "Similar findings were reported in some tumor studies, which also showed highly activated (HLA-DR+ CD38+ PD-1+) phenotypes." (PMID 35720287, 2022). "Antibody-dependent cell cytotoxicity is responsible for cell death induced by targeting the tumor with anti-CD38 antibodies, such as daratumumab." (PMID 36077708, 2022). "A high mitochondrial respiration in MM and B-ALL cells appears to be the consequence of the direct transfer of mitochondria from stromal to tumor cells; this phenomenon in MM cells is driven by CD38." (PMID 36551511, 2022). "Flow cytometry of tumor cells suspensions showed specific labeling of CD38-positive cells with JK36AF680 in both saline-pretreated and daratumumab-pretreated mice and no specific labeling of CD38-negative tumor cells." (PMID 36389758, 2022). "T-cell-mediated cytotoxic responses are only induced in CD38hi tumor cells with limited toxicity against cells expressing intermediate levels of CD38." (PMID 36139103, 2022). "CD38 is also expressed by in multiple different cell types of innate and acquired immunity, including both, tumor promoting cells and cells with cytotoxic activity." (PMID 36405759, 2022). "For example, within the tumor microenvironment, expression of CD38 in general is limited to tumor-infiltrating immune cells (TIICs)." (PMID 35677882, 2022). "Of interest, FTL004 showed ignorable binding to CD38 on human RBCs in contrast to tumor cells, even at concentrations up to 30 μg/mL." (PMID 36581954, 2022). "In a preclinical study, CAR T cells against CD38 exhibit anti-tumor activities for MM cells and xenografts." (PMID 35765110, 2022). "The NAD+-CD38-cADPR-Ca2+ axis, based on the ectoenzyme activity of CD38, regulates the tumor microenvironment by a series of reactions following Ca2+ flux." (PMID 35342342, 2022).
tumor (continued). "While daratumumab is described to mediate potent CDC of CD38-expressing tumor cells and only slightly inhibiting CD38 enzymatic activity, isatuximab inhibits app." (PMID 35784366, 2022). "CD38 expression, a T cell activation marker with conflicting roles in tumor immunology, was diminished in edited CD4+ and CD8+ TILs (p ≤ 0.0001 and p ≤ 0.0098, respectively)." (PMID 35141398, 2022). "The CD38-CAR T cells significantly reduced tumor burden and slowed disease progression (all mice had residual tumors at the end of the study)." (PMID 35765110, 2022). "We observed a strong correlation between the C18 T cell cluster and the M7 TAM cluster, both of which were significantly increased in tumor tissue and, more importantly, both of which were highly expressed in CD38." (PMID 35725444, 2022). "Further experiments showed that CD38 overexpression in tumor cells resulted in the suppression of CD8+ T cell cytotoxic function through adenosine receptor signaling both in vitro and in vivo." (PMID 36078044, 2022). "Here we show that JK36 also detects CD38-expressing tumor cells with greater sensitivity than monoclonal antibody HIT2PerCP/Cy5.5 which is currently being used in flow cytometric assays to assess treatment response in patients receiving daratumumab." (PMID 36389758, 2022). "In hematological cancers, CAR-NK cell products have been designed to target Tregs (directed against CD25 or CD38) or MSCs (against CD38) to restore tumor-infiltrating NK cell activity." (PMID 35990652, 2022). "The anti-CD38 monoclonal IgGκ antibody daratumumab has direct tumor targeting and immunomodulatory mechanisms of action." (PMID 36446823, 2022). "Combination therapy with anti-PD-L1 antibody and the flavonoid rhein (an uncompetitive CD38 inhibitor) dramatically inhibited tumor growth." (PMID 36078044, 2022). "A very recent study showed the prognostic value of tumour-infiltrating B lymphocytes along with CD38 and plasma cells in TNBC." (PMID 36536459, 2022). "In the tumor microenvironment (TME), CD38 regulates the activation of tumor associated microglia/macrophages (TMMs) through the increase of calcium concentration mediated by cADPR." (PMID 35251964, 2022). "Antibody-dependent cell cytotoxicity occurs after targeting the neoplasms with anti-CD38 antibodies, such as isatuximab or daratumumab." (PMID 36077708, 2022). "In lung cancer patients, high densities of mature dendritic cells (Lamp+) positively correlated with infiltration of activated CD8+ T cells (CD69+ CD38+) and with an effector memory phenotype that localized in the tumor nest, close to target tumor cells." (PMID 35874810, 2022). "CD38 expression on tumor-associated macrophages (TAMs) was significantly higher than PDL1, and CD38+ TAMs were closely associated with immunosuppression." (PMID 35725444, 2022). "Pretreatment with JK36-hcAb resulted in a significant decrease in CD38-positive tumor signal intensities." (PMID 36389758, 2022). "In a small series of MF patients, CD38 expression was suggested to correlate with the stage, being higher in the skin infiltrate of patients with tumor stage with respect to that found in patients with patch/plaque stage disease." (PMID 35251370, 2022). "The anti-CD38 antibody daratumumab is a human IgGκ monoclonal antibody targeting CD38 with a direct on-tumor and immunomodulatory mechanism of action." (PMID 35330161, 2022). "Prior studies have identified that ATRA can upregulate CD38 expression in various tumor cells, including APL and MM." (PMID 36313735, 2022). "In keeping with this, micromolar affinity CARs with specificity for ICAM-1 or CD38 outperformed their nanomolar counterparts in discriminating between normal and transformed cells, while maintaining strong efficacy against tumour cells." (PMID 35883636, 2022). "Extensive studies in hematological malignancies highlight that, beyond simply a surface biomarker, CD38 transduces pathways which can promote tumor survival, expansion, and metastasis." (PMID 36139103, 2022).